OR56A1 (olfactory receptor family 56 subfamily A member 1)
Description:
Odorant receptor.
Synonyms: OR11-75
Gene: Protein-coding gene on chromosome 11 (6,019,336 to 6,034,338, reverse strand). Ensembl gene ENSG00000180934.
Subcellular location: Cell membrane
Pathways (Reactome):
Sensory Perception: Expression and translocation of olfactory receptors
Genetic constraint (gnomAD): Missense variants: 333 observed, 367.1 expected, observed/expected ratio (o/e) 0.91, 90% interval 0.83 to 0.99. Synonymous variants: 162 observed, 154.24 expected, observed/expected ratio (o/e) 1.05, 90% interval 0.92 to 1.2.
Homologues: Orthologues: chimpanzee OR56A1 (99% identical), dog OR56A1 (93% identical), macaque OR56A1 (93% identical), rabbit OR56A1 (55% identical), zebrafish adra1ab (17% identical), Caenorhabditis elegans ser-5 (16% identical), zebrafish adra2da (15% identical), zebrafish adra2db (15% identical). Paralogues in human: OR56A4 (83% identical), OR56A5 (79% identical), OR56A3 (78% identical), OR13F1 (30% identical), OR5T1 (30% identical), OR5T3 (29% identical), OR5T2 (27% identical), ADRB1 (18% identical), ADRA1B (16% identical), ADRA2A (16% identical), ADRB3 (16% identical), DRD2 (16% identical), and 6 more.